CD40 (CD40 molecule)
Diseases named in the same sentence as CD40 in open-access papers (continued):
Sharing a sentence is not in itself a finding about the gene and the disease.
cancer (continued). "Over the last decade, ICIs have made a huge splash in cancer treatment by targeting immune checkpoints like PD‐L1, CD40, and CTLA‐4." (PMID 36083778, 2022). "Similar to cancer vaccines, the format of the antigen will be an important consideration for the timing of CD40 stimulation." (PMID 34282297, 2022). "For membrane protein activation and its related cancer treatment, targeting CD40 was investigated in NCT00101166 and NCT01433172 trials." (PMID 35453676, 2022). "Stimulation of CD40 is also of considerable therapeutic interest, especially in cancer immunotherapy." (PMID 36361658, 2022). "CD40-activated B (CD40-B) cells are thought to be an encouraging alternative to DCs as skilled APCs for antigen-specific cancer immunotherapy." (PMID 35967441, 2022). "On the opposite side, the stimulation of CD40 through agonistic antibodies has been regarded as a promising approach for cancer treatment." (PMID 36437950, 2022). "Our findings have unravelled more multifaceted properties for the CD40/CD40L dyad by providing novel evidence of direct TNFR crosstalk that drives rapid carcinoma cell-specific death." (PMID 36291141, 2022). "In this article, we focus on CD40 expression and immunity in cancer, agonistic human CD40 antibodies, and their pre-clinical and clinical development." (PMID 33804039, 2021). "The mechanism of anti-CD40L antibodies in cancer therapy is to enhance the immune system through the downstream effects of CD40 activation and marking malignant cells for destruction." (PMID 34446808, 2021). "In cancer, CD40 has been found in nearly all B-cell malignancies and many solid tumors, where it induces a direct cytotoxic effect in the absence of immune accessory cells." (PMID 33535618, 2021). "Many cancer immunotherapies using CD40 agonists to therapeutically activate DCs and other myeloid cells have been developed to date." (PMID 33499256, 2021). "In particular, for maturation markers, CD40 expression in DCs was dramatically induced in both cancer tissue and spleen from Poly6 challenged mice." (PMID 33499256, 2021). "In malignant tumors, CD40 expression is ubiquitously observed in most B cell malignancies and various solid tumors." (PMID 34167573, 2021). "As monotherapy, anti-CD40 shows minimal clinical activity in patients with cancer, which is the impetus for ongoing studies testing combinations with chemotherapy, radiation, and other immunotherapies." (PMID 34101617, 2021). "CD40 is a 45–50 kD glycoprotein expressed on the surface of B-lymphocytes and dendrite cells as well as cancer cells." (PMID 34679012, 2021). "CD40 remains an attractive target for cancer immunotherapy, representing a key component of both the innate and adaptive immune response." (PMID 33392713, 2021). "Overall, in this study, we demonstrate that the use of IBM with IA-like anti-CD40 can significantly enhance in situ vaccination during radiotherapy across different cancer models." (PMID 34765538, 2021). "Consistent with this notion, our data demonstrate that Poly6, a new CD40 inducer, also leads to an enhanced cancer inhibition with anti PD-L1 Ab." (PMID 33499256, 2021). "In this study, we systematically characterized the expression and clinical relevance of CD40 across a variety of normal tissues and cancer types." (PMID 34758832, 2021). "Contemporaneous developments in smart in situ drug delivery technology such as smart radiotherapy biomaterials have highlighted the potential for smart delivery of anti-CD40 and other IA to boost cancer treatment outcomes." (PMID 34765538, 2021). "We confirmed that CD40, a promising target for cancer immunotherapy, was regulated by methylation of its promoter region in colon cancer tissues and cell lines." (PMID 34184409, 2021). "Among the 23 cancer types screened, CD40 downregulation was observed in 11 malignancies compared to corresponding normal tissues, including brain, breast, lung, colon, ovary, esophagus, skin, prostate, uterus, endometrium, and blood cancers." (PMID 34758832, 2021).
cancer (continued). "The widespread expression of CD40 in carcinomas indicates a possible role for this receptor in the pathogenesis of cancer." (PMID 34445576, 2021). "CD40 is largely expressed in various types of carcinomas including breast, ovarian, nasopharyngeal, colon, lung, bladder and also RCC." (PMID 34445576, 2021). "Remarkably, 341G2 hIgG2 was found to exhibit four times higher potency than CP870,893 which remains the most agonistic anti-CD40 mAb to be tested clinically to date, capable of delivering some objective partial responses in cancer patients." (PMID 32442402, 2020). "Phagocytosis was proven, using 5-chloromethylfluorescein diacetate (CMFDA), to pre-label cancer cells and, more importantly, DC maturation was documented by the increased expression of co-stimulatory molecules CD40, CD80 and CD86." (PMID 32120810, 2020). "Given the widespread expression of CD40 in immune cells, it is important to characterise its effects on immune cells and immune regulation to better understand the potential of mCD40L as a cancer therapeutic." (PMID 31941968, 2020). "CD40 is an important tumor necrosis factor receptor (TNFR) family protein for the development of antitumor response against cancer cells, apart from its role in the regulation of the immune system as a costimulatory molecule." (PMID 32256143, 2020). "A clinical trial is being initiated for patients with cancer using an intralesional anti-CD40 in combination with CIV rhIL-15." (PMID 32508818, 2020). "Other reports revealed that the CD40/CD154 signaling pathway was a key factor for metastasis-related transforming growth factor-beta (TGF-beta) production in cancer cells and also for matrix metalloproteinases secretion in aorta and podocytes." (PMID 32325684, 2020). "A wide range of preclinical studies using immunocompetent cancer mouse models so far underscore CD40-directed therapies as a next-generation immune-modulating therapy." (PMID 33505304, 2020). "In preclinical models, CD40 agonists have demonstrated a significant ability to activate anti-cancer immunity, overcome immune checkpoint inhibition resistance, and work in concert with other immune based treatments." (PMID 32059711, 2020). "Preclinical data have demonstrated that CD40-activated B cell-based cancer immunotherapy induces effective antitumor immunity; however, CD40 agonistic antibodies rely on combination therapy strategies." (PMID 33505304, 2020). "Extensive research has been conducted regarding CD40(L)-directed immunotherapy in cancer, recently reviewed by Li and colleagues." (PMID 33198327, 2020). "Previously, we have shown that mCD40L can directly induce apoptosis in CD40-expressing carcinomas, through a mechanism involving sustained activation of the pro-apoptotic JNK pathway and downregulation of the pro-survival PI3K/AKt pathway." (PMID 31941968, 2020). "Our finding that mCD40L significantly up-regulates expression of several transcripts involved in immune responses in CD40-expressing carcinoma cells promoted us to investigate the effects of mCD40L compared with sCD40L on DC maturation and activation." (PMID 31941968, 2020). "The stimulation of CD40 on cancer cells by recombinant soluble (rs) CD40L can suppress cell proliferation and induce apoptosis in vitro and in vivo." (PMID 31417652, 2019). "CD40 agonists mediated an enhancement of adaptive antitumor immunity in preclinical mouse models in various cancer types." (PMID 30158932, 2018). "CD40 agonist mAbs are being investigated for cancer treatment, whereas antagonistic mAbs are under investigation for the treatment of autoimmune and inflammatory conditions." (PMID 29576376, 2018). "CDX-1140 is a fully human IgG2 agonist anti-CD40 mAb that activates dendritic cells (DCs) and B cells in an Fc receptor independent manner and has potent antitumor activity against CD40-expressing cancer cells." (PMID 30400822, 2018).
cancer (continued). "Systemic activation of CD40 receptor, induced by administration of agonistic CD40 antibodies, has shown signs of activity in cancer patients, but dose-limiting toxicities have impaired the efficacy." (PMID 30400822, 2018). "We clarified the alterations of mRNA of major immune regulators PD-L1, FOXP3, CD80, CD40, and CD14 in PBMCs of cancer patients and the association of these alternations with disease progression." (PMID 26942414, 2017). "CD40 mAbs have demonstrated antitumor T-cell responses in mouse models of cancer and in clinical trials." (PMID 28769933, 2017). "CD40 signalling can synergise with chemotherapy in preclinical cancer models, and early clinical studies are promising." (PMID 28619093, 2017). "Data from this study offer strong support for the development of CD40-targeting vaccines for other cancers in the future." (PMID 28133621, 2016). "Nonetheless, data from our and other recent studies support the development of CD40-targeting vaccines against other cancers." (PMID 28133621, 2016). "MiR-486-5p is dysregulated in many types of cancer and is involved in NF-kB signaling and in CD40 pathways." (PMID 27223429, 2016). "This study provides a further understanding of the differential effects of membrane-expressed and soluble CD40L in the context of CD40-expressing carcinomas." (PMID 26986513, 2016). "Ligation of CD40 with CD40L was recently shown to activate the NFκB pathway resulting in enhanced IFN-I response in carcinoma cells." (PMID 27716849, 2016). "Given the cell growth-inhibitory effect of mCD40L on CD40-positive carcinomas, we sought to investigate the contribution of NORE1A to these effects." (PMID 26986513, 2016). "We show here a novel strategy for the development of recombinant vaccines carrying cyclin D1 cancer antigens that can be targeted to dendritic cells (DCs) via CD40." (PMID 25888530, 2015). "The contribution of the CD40 signaling in cancer, and prospects offered by targeting the CD40 signaling for cancer treatment have recently been underlined and reviewed." (PMID 25763299, 2015). "Utilizing agonist mAbs to target select TNFR members has proven an effective treatment modality in preclinical cancer models, which has led to translational clinical studies of agonist mAbs specific for CD40, CD137, and OX40." (PMID 26500773, 2015). "To examine the effect of human constant regions on agonistic activity, we used the anti-human CD40 mAb ChiLob 7/4, currently in phase 1 clinical trial in cancer patients." (PMID 25500122, 2015). "Delivery of antigen via mAb to CD40 has been shown to induce antigen-specific immune responses and provide protection against cancer, as well as control HIV infection in vitro." (PMID 25888530, 2015). "We describe how targeted delivery of CD40L to cancer antigens can be exploited to achieve localized activation of CD40 and can be modified to exert additional anti-cancer action via the targeting domain." (PMID 24741998, 2014). "Widespread expression of CD40 in human carcinomas also supports the role of this ligand in cancer pathogenesis." (PMID 24745825, 2014). "Other authors have investigated the significance of CD40 expression on cancer cells of the urinary tract." (PMID 25117071, 2014). "CD40 has been explored as a target for the treatment of several forms of cancer using recombinant soluble CD40L (sCD40L) or agonistic therapeutic antibodies (Abs)." (PMID 24741998, 2014). "mCD40L interaction with CD40-positive cancer cells was accompanied by increased production of IL-8 by transformed cells." (PMID 25117071, 2014). "Systemic injection of anti-CD40 can produce detrimental side effects in cancer patients and liposome based delivery of anti-CD40 to the TDLN has been shown to reduce harmful side effects often observed in systemic treatment." (PMID 25380524, 2014). "Since CD40L and CD40 molecules are strong immunostimulators, they are considered useful in anti-cancer therapy." (PMID 25117071, 2014).
cancer (continued). "Transduction of Rad-hCD40L to CD40-positive cancer cells of the urinary bladder, uterine cervix, and ovary inhibits strong proliferation of these cells." (PMID 25117071, 2014). "High signal (the cell has many CD40 molecules) indicates apoptosis of cancer cells, whereas low signal (a small number of receptors) CD40L promotes cancer growth." (PMID 25117071, 2014). "Both pre-clinical and clinical studies have highlighted toxicity concerns with the use of agonistic CD40-targeted agents for treating cancer." (PMID 24741998, 2014). "These previous studies as well as the current approach support the further clinical translation of cancer therapies targeting CD40." (PMID 24664420, 2014). "Stimulation of CD40 can augment anti-cancer T cell immune responses by triggering effective activation and maturation of antigen-presenting cells (APCs)." (PMID 24741998, 2014). "Apart from its effect on the body immunity, the CD40L/CD40 system can inhibit cancer growth via enhanced apoptosis of cancer cells." (PMID 25117071, 2014). "In our early publications, we focused on the role of CD40 on B cells, even though others and we early on had found that CD40 is expressed on epithelial cells and carcinomas." (PMID 25324844, 2014). "First characterized as a major marker on carcinoma cells, CD40 was next shown to be a key molecule shared by endothelial cells and most APCs, including B-cells, monocytes and DCs." (PMID 25479079, 2014). "The adjuvant effect of CD40 ligation, reflected by DC activation, prompted the application of agonistic anti-CD40 antibodies for cancer therapy." (PMID 23450201, 2013). "For CD40-activated B cells of healthy donors and of cancer patients the migration capacity has been shown." (PMID 22592077, 2012). "An important advantage of CD40-activated B cells is that they can be highly expanded at relatively low cost from small amounts of peripheral blood even from cancer patients." (PMID 22592077, 2012). "The capacity of CD40-activated B cell-based cancer vaccine to induce CD4+ and CD8+ T cell responses also has been shown in vivo in mice and a large animal model in dogs." (PMID 22592077, 2012). "Human B cells acquire potent immunostimulatory properties when activated via CD40 and have been shown to be an alternative source of antigen-presenting cells (APCs) for cellular cancer vaccines." (PMID 22592077, 2012). "Overall, our clinical and immunological results suggest that cell-based CD40 cancer vaccination synergizes with chemotherapy to improve clinical outcome in this disease." (PMID 21904611, 2011). "Currently, the mechanisms of the multifaceted roles of CD40 in cancer are still not completely understood." (PMID 21912605, 2011). "Overall, these clinical and immunological results suggest that cell-based CD40 cancer vaccination is safe and synergizes with chemotherapy to improve clinical outcome in canine NHL." (PMID 21904611, 2011). "Taken together, the CD40 pathway provides an opportunity to harness different anti-cancer approaches into one therapy and offers an attractive option for clinical trials." (PMID 20211016, 2010). "Matching our observations, they proposed that CD40 provides “insight into progression of cancer from normal epithelium”; our proposed methodology is revealing this fact as well." (PMID 20805891, 2010). "In carcinoma cells the level of CD40 engagement influences the physiological outcome with low levels of ligation promoting cell survival/proliferation and high levels inducing growth arrest/apoptosis." (PMID 20211016, 2010). "Here we show that the mutated, cleavage-resistant form of CD40L is a more potent inducer of apoptosis than wild-type ligand in CD40-positive carcinoma cell lines." (PMID 20211016, 2010). "As expected this virus failed to generate soluble ligand, resukted in a higher level of membrane-bound ligand expression, and induced greater cell death than wild-type ligand in CD40-positive carcinoma cells." (PMID 20211016, 2010).
cancer (continued). "We, and others, have demonstrated that in addition to immune cells, CD40 is expressed in malignant haemopoietic cells and a number of carcinomas." (PMID 20211016, 2010). "In carcinoma cells the physiological outcome of CD40 ligation depends on the level of receptor engagement with low levels promoting cell survival and high levels inducing cell death." (PMID 20211016, 2010). "We next sought to investigate the ability of membrane-bound CD40L to induce apoptosis in CD40-positive carcinomas." (PMID 20211016, 2010). "Here we have demonstrated the ability of a mutant non-cleavable CD40L delivered via a replication-deficient adenovirus vector to directly induce cell death in CD40 expressing carcinoma cells." (PMID 20211016, 2010). "Unlike soluble CD40L, RAd-delivered CD40L is able to directly induce apoptosis in CD40-positive carcinoma cells (EJ, AGS) as assessed by Annexin V staining." (PMID 20211016, 2010). "The direct effect of wild-type and cleavage-resistant CD40L on cell survival was examined in CD40-positive carcinoma cell lines." (PMID 20211016, 2010). "The phenotypic profile of the DCTs and DCTIs generated from monocytes obtained from cancer patients in the present study show similar changes, except for low expression of CD40." (PMID 19298672, 2009). "Previous studies, including work from our group, demonstrated that immunoadjuvants like anti-CD40 induce antitumor effects in different cancer models, including the lung, while apoptosis induced by radiation initiates further enhancement of immune cell activation." (PMID 40278452, 2025). "To investigate whether activating CD40 in TAg+ cancer cells directly induces cell death, as described for human carcinoma cells, we stimulated TGFβ pretreated and untreated cancer cells with multimeric CD40L." (PMID 40397730, 2025). "Consistent with this notion, agonistic CD40 antibodies were shown to increase T-cell mediated cancer death and, in combination with chemotherapy, may rescue ICI sensitivity." (PMID 40230862, 2025). "Thus, optimizing dosage regimens and managing adverse effects (e.g., cardiovascular toxicity) are essential in future CD40 agonist-based cancer therapies." (PMID 41268556, 2025). "Last, enhancing the presence of CD40L+CD8+ T cells or sensitizing cancer cells to CD40-induced cytotoxicity with drugs could serve as effective strategies to use this additional antitumor mechanism." (PMID 40397730, 2025). "In addition, it has been reported that CD40 stimulation of macrophages directly mediates cancer cell killing as well as microenvironment collapse." (PMID 40108724, 2025). "Studies targeting CD40 aim to enhance anti-cancer immune responses." (PMID 41182434, 2025). "It was observed that the immune system was leveraged by combining RT and LIFE Biomaterial loaded with anti-CD40, which could be beneficial for cancer patients." (PMID 41155910, 2025). "It is under investigation whether CD40-targeting therapy can improve the outcomes of cancer patients." (PMID 39516356, 2024). "CD40 activation and using CD40 agonists are a novel clinical opportunity for cancer immunotherapy." (PMID 38835055, 2024). "CD40 has attracted much attention as a cancer therapy target." (PMID 39516356, 2024). "The CD40/CD40L axis plays a significant role in cancer development." (PMID 39625893, 2024). "Elevated levels of CD40 have been reported in some types of cancer." (PMID 39625893, 2024). "In addition, cancer cells can undergo apoptosis induced by CD40 intracellular signaling, generating neo-antigens to help boost anti-cancer immune responses." (PMID 38539546, 2024). "Several first-generation CD40 agonist Abs were developed and tested in patients with cancer." (PMID 38883779, 2024). "Thus, we investigated the utility of R848 (Resiquimod), an innate immune agonist of the TLR7/8 pathway that is commonly used in cancer immunotherapy, in enhancing the immune-stimulatory effects of CD40 agonism." (PMID 39033322, 2024).